FGF22 (fibroblast growth factor 22)
Diseases named in the same sentence as FGF22 in open-access papers:
FGF22 is named in the same sentence as 35 diseases in open-access papers, as found by Europe PMC text mining. Sharing a sentence is not in itself a finding about the gene and the disease. The quoted sentences say what the papers report.
breast carcinoma (4 papers, 2017 to 2024). "For example, FGF7, FGF10, and FGF22 bind exclusively to FGFR2 IIIb, with FGFR2 IIIb/FGF10 being highly associated with breast cancer development." (PMID 39596875, 2024). "CLK1 and FGF22 are oncogenes in cancer and their inhibition leads to the inhibition of breast cancer growth in cell culture and xenograft models." (PMID 34066541, 2021). "Breast cancer is the major cause of cancer death among the female worldwide, gene BRCA1 and FGF22 are enriched in this pathway." (PMID 29170526, 2017). "In conclusion, the FGF7 family—except for FGF22 whose role in breast cancer has not been reported yet—plays a crucial role not only in the formation of mammary gland during development, but also in breast cancer initiation, progression and resistance to therapies." (PMID 35193394, 2022).
depression (4 papers, 2017 to 2025). "The observed association between FGF-22 and interleukin-1β in depression suggests a potential role in diabetes-related inflammation." (PMID 40943671, 2025). "Currently, among the twenty-two identified FGFs, FGF2, FGF9, FGF21, and FGF22 have been found to be associated with depression." (PMID 30804785, 2019). "As a member of FGF family, FGF22 has been found to be significantly associated with the occurrence of epilepsy, cancer, depression and other diseases as well as embryonic brain development." (PMID 30804785, 2019). "In order to provide further insights into the molecular mechanisms underlying depression-like behaviors, in this article, we ask cell-type specific roles of FGF22 in the regulation of affective behavior using CA3-specific FGF22 knockout mice." (PMID 29311892, 2017). "FGF22 is expressed mainly in the skin and brain, and the deletion of endogenous FGF22 induced depression-like behavior, as shown by the FST, TST, and SPT." (PMID 32184729, 2020). "In a controlled study of 90 first-onset depressive patients and 90 healthy volunteers, decreased serum FGF22 levels were found in depressive patients, and these levels were negatively correlated with the patients’ scores of Hamilton Depression Scale." (PMID 30804785, 2019). "FGF22 knockout mice models display depression-like behaviors (including despair and anhedonia) in forced swim test, tail suspension test and sucrose preference test." (PMID 30804785, 2019). "Our study raises a possibility to target FGF22 in CA3 as a possible treatment of certain aspects of depression." (PMID 29311892, 2017). "FGF22 null mice display a depression-like phenotype: increased passive stress coping behavior and anhedonia." (PMID 29311892, 2017). "It is likely that there are various molecular and pathophysiological changes that contribute to depression-like behaviors, and we propose that synapse development mediated by CA3-derived FGF22 is one such underlying mechanism." (PMID 29311892, 2017). "As a behavioral consequence, FGF22 null mice show depression-like behaviors such as increased passive stress-coping behavior and anhedonia." (PMID 29311892, 2017). "Finally, as a behavioral consequence of FGF22 inactivation, FGF22 null mice display depression-like behaviors such as increased passive stress-coping behavior and anhedonia." (PMID 29311892, 2017). "Here, we mainly concentrated on the reported depression-related FGF system members, including FGFR1, FGF2, FGF9, FGF21, and FGF22." (PMID 30804785, 2019). "Although the molecular mechanisms of FGF-22 are not fully elucidated, its involvement in depression has been reported." (PMID 40943671, 2025).
Hypertension (2 papers, 2022 to 2025). The presence of chronic increased pressure in the systemic arterial system. "A single-nucleotide polymorphism in the FGF-22 gene, associated with hypertension and height, is rs8109113." (PMID 40943671, 2025). "In diabetic patients, the observed lower concentrations of FGF-2 and FGF-22 could indicate a significant association with hypertension, emphasizing the interconnected nature of these metabolic conditions." (PMID 40943671, 2025). "Interestingly, rs8109113 in the FGF22 gene was associated with both hypertension and height, and 17 SNPs in FGF10, FGF18, and FGF2 were associated with both osteoporosis and height." (PMID 35980984, 2022). "Statistical analysis revealed a significant relationship between FGF-2 and FGF-22 concentrations and hypertension (p = 0.03; p = 0.01)." (PMID 40943671, 2025). "Similarly, statistically significant differences in median FGF-22 concentrations were found in relation to hypertension status (p = 0.01)." (PMID 40943671, 2025). "Similar to FGF-2, lower FGF-22 levels were observed in patients with diabetes and hypertension; however, no prior reports have linked FGF-22 to hypertension." (PMID 40943671, 2025). "The observed alterations in FGF-2, FGF-19, FGF-22, and FGF-23 concentrations—particularly their associations with hypertension, obesity, nephropathy, and joint degeneration—support their role not only in the pathogenesis but also in the clinical stratification of diabetic complications." (PMID 40943671, 2025). "Similarly, the FGF2, FGF4, FGF10, FGF18, and FGF22 genes, which showed interactions with the FGFRL1 gene, were associated with height, hypertension, and osteoporosis." (PMID 35980984, 2022). "The FGF10, FGF18, FGF2, FGF4, and FGF22 genes, which interact with FGFRL1, were correlated with height, hypertension, and osteoporosis." (PMID 35980984, 2022). "Patients with hypertension exhibited lower median levels of FGF-22 compared to individuals without hypertension." (PMID 40943671, 2025).
lung carcinoma (2 papers, 2021 to 2024). "This was followed by FGF22 (fibroblast growth factor 22), which is also a prognostic biomarker for lung cancer." (PMID 38790260, 2024).
Anxiety (1 paper, 2017). Intense feelings of nervousness, tension, or panic often arise in response to interpersonal stresses. "FGF22 null mice display normal motor, anxiety and social cognitive tests, indicating a role of FGF22 specifically in affective behaviors." (PMID 29311892, 2017). "FGF22 null mice do not show any changes in anxiety-like behaviors, social cognition and motor phenotypes." (PMID 29311892, 2017). "FGF22 null mice do not display defects in motor and exploratory behaviors, anxiety-like behaviors and social behaviors or memory." (PMID 29311892, 2017).
Arthritis (1 paper, 2025). Inflammation of a joint. "A significant correlation was also observed between the concentrations of FGF-22 and FGF-23 and arthritis (p = 0.01; p = 0.02)." (PMID 40943671, 2025). "The analysis revealed a significant difference in median FGF-22 concentrations between FGF-22 concentration and arthritis (p = 0.01)." (PMID 40943671, 2025).
Ataxia (1 paper, 2022). Ataxia refers to impaired coordination of voluntary muscle movement. "The pathway related to growth factors (FGF4, FGF22, and PDGFD), RTK, and PLCB4 was also associated with visual processing defects, ataxia, absence seizures, epilepsy, and Huntington's disease." (PMID 36457060, 2022).
cardiac hypertrophy (1 paper, 2021). "The FGF18 and FGF22 genes are known to play a role in heart development and physiological processes while the MYC gene is implicated in angiogenesis, cardiomyogenesis, apoptosis, oxidative stress response and plays a major role in initiating and maintaining cardiac hypertrophy and contractility." (PMID 33788842, 2021).
deafness (1 paper, 2022). An inherited or acquired condition characterized by the complete loss of the ability to hear from one or both ears. "Our research concluded that FGF22 deletion caused HHL by affecting the function of IHC ribbon synapses and may offer a novel therapeutic target to meet an ever-growing demand for deafness treatment." (PMID 35966010, 2022).
diabetes (1 paper, 2025). "Given the limited number of studies on FGF-22 in the context of diabetes, its role remains largely unexplored." (PMID 40943671, 2025). "One possible mechanism is the interplay between FGF-22 and pro-inflammatory cytokines, such as interleukin-1β (IL-1β), which are known to contribute to insulin resistance, beta-cell dysfunction, and vascular inflammation in diabetes." (PMID 40943671, 2025). "However, based on emerging evidence from experimental models, it is reasonable to hypothesize that FGF-22 may interact with inflammatory mediators involved in the pathogenesis of diabetes-related complications." (PMID 40943671, 2025). "In light of these limitations, further large-scale studies with more homogeneous cohorts, incorporating medication tracking, and longitudinal follow-up are necessary to validate the current results and clarify the mechanistic and prognostic roles of FGF-2, FGF-19, FGF-22, and FGF-23 in diabetes." (PMID 40943671, 2025). "Given the clinical relevance of glycemic control, Spearman’s rank correlation analysis was conducted to assess the relationship between glycated hemoglobin (HbA1c) levels and concentrations of selected fibroblast growth factors (FGF-2, FGF-19, FGF-22, and FGF-23) in patients with diabetes (n = 73)." (PMID 40943671, 2025). "FGF-2, FGF-19, FGF-22, and FGF-23 likely significantly impact diabetes and its complications." (PMID 40943671, 2025). "When analyzed separately by diabetes type, in patients with type 2 diabetes (n = 73), age showed negative correlations with FGF-2 (ρ = −0.27, p = 0.022) and FGF-22 (ρ = −0.32, p = 0.005)." (PMID 40943671, 2025).
epileptic seizures (1 paper, 2012). "Furthermore, FGF22 deficient mice, generated commercially (Deltagen, San Mateo, CA), are resistant to pentylenetetrazol-induced epileptic seizures, though lack of FGF22 does not affect behaviour in unchallenged mice." (PMID 22737238, 2012).
hair follicle diseases (1 paper, 2025). "An in-depth exploration of the FGF22-mediated mechanism is conducive to clarifying the biological principles of hair follicles and providing new theoretical strategies for the treatment of hair follicle diseases and skin tissue engineering." (PMID 41301478, 2025).
hair loss (1 paper, 2025). "These subsequent research directions are of great significance for overcoming the limitations of current research, deeply understanding the mechanism of action of FGF22, and providing more effective theoretical basis and treatment methods for hair loss treatment." (PMID 41301478, 2025).
hearing loss (1 paper, 2020). "Hence, our data suggest that the ribbon synapses may be regulated by FGF22/calcium/CalN/MEF2D signaling, which implied novel therapeutic targets for hearing loss." (PMID 32271716, 2020).
heart defects (1 paper, 2019). "Although FGF22 was reported most in the neurology, we detected its variant in our patient populations with heart defects and speculated that FGF22 may have some similar function with FGF10 in heart development." (PMID 30745907, 2019).
liver cancer (1 paper, 2019). An epithelial or non-epithelial malignant neoplasm that arises from the liver. "In patients with liver cancer, FGFs (FGF2, FGF4, FGF5, FGF9, and FGF22) are overexpressed." (PMID 31031647, 2019).
metabolic syndrome (1 paper, 2023). A cluster of metabolic risk factors for CARDIOVASCULAR DISEASES and TYPE 2 DIABETES MELLITUS. "PIK3R2, STRA8, FLT1, DMRT1, FGF22, NR5A2, and FLT genes were up-regulated in metabolic syndrome after exercise." (PMID 37053002, 2023). "PIK3R2, STRA8, FLT1, DMRT1, FGF22, NR5A2, and FLT were up-regulated and PRDM14, POU5F1, and KDR were down-regulated in metabolic syndrome after exercise." (PMID 37053002, 2023).
Obesity (1 paper, 2025). Accumulation of substantial excess body fat. "In this context, the inverse relationship observed between FGF-22 and BMI may reflect an underlying mechanism in which FGF-22 is downregulated in states of chronic low-grade inflammation, such as obesity." (PMID 40943671, 2025). "A statistically significant difference was also found between the concentrations of FGF-19 and FGF-22 (p = 0.001; p < 0.001) in the serum of people with normal weight and people with overweight and obesity." (PMID 40943671, 2025). "Furthermore, the study highlights that reduced levels of FGF-19 and FGF-22 in individuals suffering from obesity may reflect a more profound link between these growth factors and excess body weight." (PMID 40943671, 2025).
papilloma (1 paper, 2012). A benign epithelial neoplasm that projects above the surrounding epithelial surface and consists of villous or arborescent outgrowths of fibrovascular stroma. "The time when 50% of mice developed papillomas was delayed by 16 weeks in fgf22 knockout mice compared with wild type controls." (PMID 22737238, 2012). "However, classical two-step skin carcinogenesis challenge revealed that FGF22 null mice developed fewer papillomas than wild type controls, suggesting a potential pro-oncogenic role for FGF22 in the skin." (PMID 22737238, 2012). "When cohorts of fgf22 knockout female mice were subjected to two-step (DMBA/TPA) skin carcinogenesis treatment, they developed significantly less papillomas than wild type mice." (PMID 22737238, 2012). "Fgf22 wild type and knockout mice subjected to TPA treatment alone never developed papillomas." (PMID 22737238, 2012). "Therefore we hypothesised that in fgf22 knockout mice, where FGF7 and/or FGF10 do not have to compete with FGF22 for receptor binding, it may allow stronger FGF-mediated cytoprotective signalling and, consequently, reduced papilloma formation." (PMID 22737238, 2012).
type 1 diabetes (1 paper, 2025). "In patients with type 1 diabetes (n = 31), age correlated negatively with FGF-22 (ρ = −0.39, p = 0.027)." (PMID 40943671, 2025).
type 2 diabetes (1 paper, 2025). "For instance, the identification of reduced FGF-19 or FGF-22 levels in overweight individuals or those with type 2 diabetes could indicate a higher risk of metabolic decompensation and musculoskeletal deterioration." (PMID 40943671, 2025). "The study observed a difference in the relationship between the median serum concentrations of FGF19 and FGF22 in patients with type 1 and type 2 diabetes, as well as in the control group (p < 0.001; p < 0.001)." (PMID 40943671, 2025). "The study observed a significant relationship between the levels of FGF19 and FGF22 in the serum of patients with type 1 and type 2 diabetes, as well as in the control group (p < 0.001; p < 0.001)." (PMID 40943671, 2025). "In our study, FGF-22 concentrations differed significantly between groups, with lower levels observed in individuals with type 2 diabetes compared to those in the control group." (PMID 40943671, 2025). "Additionally, the study group with type 2 diabetes showed a significantly lower FGF-22 concentration compared to the control group (p < 0.001)." (PMID 40943671, 2025). "The findings of this study suggest that fibroblast growth factors, specifically FGF-19 and FGF-22, may play crucial roles in the pathophysiology of both type 1 and type 2 diabetes." (PMID 40943671, 2025). "Overall, these results indicate that both age and BMI are consistently associated with reduced concentrations of FGF-19 and FGF-22, particularly in patients with type 2 diabetes, whereas FGF-2 and FGF-23 showed no consistent correlations with either parameter." (PMID 40943671, 2025). "In our study, the levels of FGF-2, FGF-19, FGF-22, and FGF-23 were measured in patients with type 1 and type 2 diabetes and compared with healthy controls." (PMID 40943671, 2025). "FGF-21, known to regulate glucose and lipid metabolism, was previously reported to correlate positively with triglycerides in type 2 diabetes; a similar relationship with triglycerides was observed in our study for FGF-19 and FGF-22." (PMID 40943671, 2025). "The study aimed to analyze and compare the concentrations of selected fibroblast growth factors, FGF-2, FGF-19, FGF-22, and FGF-23, in the plasma of patients with type 1 and type 2 diabetes with those of the control group." (PMID 40943671, 2025).
viral infection (1 paper, 2024). "This suggests that the FGF22 gene plays a crucial role in PRV XJ delgE/gI/TK resistance to viral infection." (PMID 38550870, 2024).
cancer (4 papers, 2017 to 2024). A tumor composed of atypical neoplastic, often pleomorphic cells that invade other tissues. "The results of our study revealed that FGF6, FGF20, FGF22, and FGF23 are crucial biomarker proteins that NSP-B specifically targets for the therapy of cancer." (PMID 38434705, 2024).
tumor (3 papers, 2012 to 2023). "One model that might explain this is that FGF22 might act to antagonise the tumour suppressive role of FGFR2b, by competing with the protective ligands FGF7 and FGF10." (PMID 22737238, 2012). "Thus the ligand and its receptor appear to have antagonizing effects, with a tumour suppressive receptor, FGFR2b, appearing to be activated by a putative oncogenic ligand, FGF22." (PMID 22737238, 2012).
infection (1 paper, 2023). The state of being infected such as from the introduction of a foreign agent such as serum, vaccine, antigenic substance or organism. "In vitro infection of cortical neurons and quantification of the relative expression of FGF22 showed a more than 105 fold increase in mRNA expression of FGF22 demonstrating the potency and efficacy of our vector (Unpaired two‐tailed t‐test, P = 0.0406; Fig EV1C and D)." (PMID 36601738, 2023).
FGF22 also shares sentences with these, for which no sentence is quoted: osteoporosis (2 papers); epilepsy (1); gastric cancer (1); Huntington disease (1); Insulin resistance (1); lymphoma (1); melanoma (1); Nephropathy (1); ovarian carcinoma (1); spinal cord injury (1).